MCL1 (MCL1 apoptosis regulator, BCL2 family member)
Diseases named in the same sentence as MCL1 in open-access papers (continued):
Sharing a sentence is not in itself a finding about the gene and the disease.
cancer (continued). "Our purpose was to better understand the finding that Thr 163 phosphorylation is associated with Mcl-1 stabilization in these and other cancer cells, but primes Mcl-1 for GSK3/phosphodegron-targeted degradation in normal fibroblasts." (PMID 23056582, 2012). "Mcl-1 is another highly expressed antiapoptotic protein in malignant tumors and has been implicated in resistance to chemotherapy through a number of signaling pathways." (PMID 22520038, 2012). "This activity and upregulation of USP9X as well as Mcl-1 have been associated with a poor prognosis and with chemoresistance in a number of cancers." (PMID 23171055, 2012). "Studies from multiple cancer cells have shown that the NOXA inhibition or MCL1 overexpression can dramatically reduce apoptosis and consequently promote the tumor viability, which suggests a possible effect of NOXA-MCL1 axis on susceptibility to cancers." (PMID 22548841, 2012). "Immunoprecipitation (IP) western blotting was employed to further explore the physical interaction between USP9X and Mcl-1 in cancer cells and a strong direct association was observed." (PMID 23171055, 2012). "Up-regulation of the apoptosis-regulatory gene Mcl-1 (myeloid cell leukemia-1) occurs in different cancer types and is linked with drug resistance to cancer therapies." (PMID 23284704, 2012). "Aberrant overexpression of Mcl-1 has been associated with poor prognosis and resistance to chemotherapy in a variety of human cancers." (PMID 20085644, 2010). "The overexpression of proapoptotic factors, eg Mcl-1, bcl-2 or bcl-xL, has been implicated in cancer development, tumour progression and therapy resistance of B-cell lymphoproliferative diseases." (PMID 17473827, 2007). "MCL1 is an anti-apoptotic protein associated with cancer and therapy resistance." (PMID 41326406, 2025). "Furthermore, the decreased stability of Mcl-1 induced by IMQ is associated not only with the production of ROS but also with the maintenance of mitochondrial integrity in cancer cells." (PMID 39272918, 2024). "MCL1 is an oncogene that is amplified in cancers and causes resistance to chemotherapy regimens." (PMID 39386614, 2024). "Furthermore, cancer-associated mutations in the CTS of Mcl-1, such as A339T and L384V, were found to enhance the interaction between the Bok CTS and Mcl-1 CTS." (PMID 38985308, 2024). "Thus, FBW7 mutations confer Taxol resistance to cancer cells due to accumulation of its anti-apoptotic substrate MCL-1." (PMID 36672454, 2023). "Meanwhile, like other Bcl-2 anti-apoptotic members, high frequency of Mcl-1 gene amplification has been observed in various human cancers and the elevated Mcl-1 protein level has also been validated in cancer tissues, which underlines the importance of Mcl-1 for cancer cell survival." (PMID 36658493, 2023). "Moreover, Mcl-1 is a pro-survival protein that has been implicated in the maintenance of chemotherapy-resistant cancer stem cells (CSCs) in TNBC11." (PMID 37481672, 2023). "The association of Mcl-1 in chemo and radiotherapy resistance in cancer cells is well-described." (PMID 36984785, 2023). "Moreover, MCL1 has been implicated in resistance to a range of cancer therapies, including those targeting the BCL-2 family of proteins, which are also involved in apoptosis regulation." (PMID 37744271, 2023). "Indeed, cancer-associated FBXW7 mutations cause resistance to anti-tubulin chemotherapeutics via accumulation of MCL1 protein." (PMID 36934104, 2023). "However, the sensitivity of Hsp90 inhibitors is limited by the level of MCL-1, which is overexpressed in some cancers due to FBXW7 mutations." (PMID 35346215, 2022).
cancer (continued). "Dina alone could induce apoptosis to some extent in cancer cells, which is likely associated with the concomitant downregulation of MCL1, Survivin, and cFLIP in cells." (PMID 35884614, 2022). "In fact, upregulation of ENO1 is associated with worse prognosis in many cancer types, which may in part be mediated by chemotherapy-induced nuclear translocation of MCL1 to drive chemoresistance, possibly through the regulation of transcription." (PMID 35042842, 2022). "Though the precise mechanism underlying Skp2 deficiency-increased FBW7 and Mcl-1 interaction remains unclear, the oncoprotein Skp2 is still an attractive anti-cancer target." (PMID 35301297, 2022). "Cancer cell resistance to apoptosis is commonly associated with overexpression of the antiapoptotic members of Bcl-2 family proteins, in particular, Bcl-2, Bcl-xL, and Mcl-1." (PMID 35008345, 2021). "STAT3 is closely associated with pathogenesis of various cancers by regulating the expression of critical genes for survival, proliferation, and angiogenesis, such as Bcl-2, Bcl-xL, Mcl-1, CCND1, and VEGF, which were important for survival, proliferation, and angiogenesis." (PMID 34335938, 2021). "We further observed that DET/DETD-35 treatment for 6 h and 12 h induced increase in the full-length form of the anti-apoptotic protein Mcl-1; however, we also observed an increase in the Mcl-1 splicing variant Mcl-1S which antagonizes Mcl-1 and plays a pro-apoptotic role in cancer cells." (PMID 33810045, 2021). "Anti-tumour effects of MCL-1 inhibition could also occur through pro-tumour immune cell depletion and cancer associated fibroblasts and such contributions to tumour suppression may only emerge in homologous experimental systems." (PMID 33785871, 2021). "Thus, despite the coincident repression of many other transcripts, MCL1 loss is inextricably linked to the anti-cancer efficacy of this class of inhibitors." (PMID 32645016, 2020). "The observed susceptibility of different cancer cells for MIM1 treatment indicates that proapoptotic effect of this small molecule may depend not only on the Mcl-1 expression but also on specification of cell type." (PMID 31432325, 2020). "Mcl-1 up-regulation is a hallmark of cancers and causes drug resistance to some cancer therapies." (PMID 33064779, 2020). "In BRAFV600E-mutated cancers, MCL-1 has been shown to be aberrantly upregulated." (PMID 32411231, 2020). "Given the effects of the Mcl-1 isoforms on apoptosis, we speculated that blocking Mcl-1L expression and inducing Mcl-1S expression would cause the cancer cells to switch to a pro-apoptotic state and restrain tumor progression." (PMID 33052877, 2020). "Importantly, FBXW7 deletion or loss-of-function mutations from patient-derived cancer cells impair the MCL-1 degradation and result in resistance to chemotherapy drugs." (PMID 32907612, 2020). "Finally, by applying a comparative oncogenomics strategy to uncover additional culprits of tumorigenesis, we identified MCL1 as a druggable cancer driver that collaborates with MYC in BRCA1-deficient TNBC." (PMID 30674894, 2019). "Studies have shown that MCL-1 plays a key role in the growth of cancer cells “escaping” drug attacks, but the underlying mechanism remains unclear." (PMID 30728351, 2019). "Although there are currently no drugs against CRL5, future experiments determining how CRL5 and MCL1 are linked could identify new drug targets and improve existing cancer treatments." (PMID 31294695, 2019). "Therefore, Mcl-1 downregulation by XPO1 inhibitor was insufficient to induce apoptosis in cancer cells but likely made cancer cells more susceptible to inhibitors targeting of Bcl-2 and/or Bcl-xL." (PMID 31113936, 2019). "Importantly, we also show that inhibition of Cdc20 promotes mitotic cell death more effectively than loss of APC/C activity through differential effects on Mcl‐1 degradation, providing an improved strategy to kill cancer cells." (PMID 29987118, 2018).
cancer (continued). "Moreover, the up-regulation of anti-apoptosis Bcl-2 family proteins including Bcl-2 (B-cell lymphoma 2) and Mcl-1 (myeloid cell leukemia 1) has been associated with anoikis resistance and highly metastasis cancer cells." (PMID 29631569, 2018). "Both myeloid cell leukemia 1 (MCL-1) and Cyclin D1, which are associated with apoptosis and cell cycle regulation, respectively, have been found to be direct targets of miR-193b in other cancers." (PMID 29719597, 2018). "Since previous studies have demonstrated that c-met and MCL-1 regulate TRAIL sensitivity to several cancers, we next investigated whether expression levels of c-met and MCL-1 were associated with TRAIL sensitivity to our PTC cell line TPC-1." (PMID 29312559, 2017). "MCL1 is highly associated with taxol resistance in malignant tumors derived from epithelial cells." (PMID 28464881, 2017). "Above all, we can hypothesize that copy‐number variations (CNVs) in BCL2L1 and MCL1 may be associated with cancer prognosis." (PMID 27264345, 2016). "MCL-1 was already shown to reduce susceptibility of cancer cells to drug-induced senescence." (PMID 26824319, 2016). "In addition to cyclin D1, rapalogs induce GSK3-dependent degradation of other oncogenic proteins such as c-Myc and Mcl-1; these effects should be tightly associated with rapalogs’ cancer therapeutic efficacies." (PMID 25797247, 2015). "Moreover, MCL-1 gene, frequently amplified in human cancers, is associated with chemoresistance and relapse." (PMID 26063499, 2015). "Overexpression of MCL-1 has been previously associated with drug resistance in cancer." (PMID 26474278, 2015). "Recent studies revealed that Mcl-1 could also be implicated in the regulation of cancer cell response to TRAIL-induced apoptosis." (PMID 24566141, 2014). "We further investigated whether evodiamine affected the levels of the Bcl-2 family members (e.g., Bax, Bcl-2, Bcl-XL and Mcl-1), which have been implicated in the regulation of intrinsic apoptotic pathway and cancer cell response to TRAIL-induced apoptosis." (PMID 24566141, 2014). "It has been reported that down-regulation of MCL1 renders cancer cells susceptible to anoikis." (PMID 24523919, 2014). "Consistent with its antitumor activity potential, FL118 selectively inhibits multiple cancer survival-associated genes (survivin, Mcl-1, XIAP and cIAP2), while inducing proapoptotic factors Bax and Bim, and showing no inhibitory effects on control genes (p21, DHFR, HTR and TK)." (PMID 23029106, 2012). "Regulated by STAT3, both Mcl-1 and survivin have been implicated in cancer growth." (PMID 22280969, 2012). "Thus, cancer cell sensitivity to ABT seems to be determined not only by the protein levels of Mcl-1, but also by how much Bak is sequestered by its association with Mcl-1." (PMID 21949692, 2011). "Increased levels of Mcl-1 have been reported in a variety of human tumors, where elevated expression is associated with disease recurrence and drug resistance (for a review, suggesting an important role played by Mcl-1 in cancer cell survival." (PMID 20626868, 2010). "The marked reduction in Mcl-1—an anti-apoptotic factor frequently associated with chemoresistance and poor prognosis in cancer patients —suggests that TDB may also sensitize GBM cells to other therapeutic agents, further enhancing its potential as an effective treatment strategy." (PMID 41154521, 2025). "Notably, MCL-1 protein overexpression was confirmed via immunohistochemistry and was significantly associated with advanced pathological stage and lymph node involvement, further supporting its role in cancer cell survival and resistance to apoptosis." (PMID 40612845, 2025). "Thus, the TRIP12/FBW7/MCL-1 axis may provide a therapeutic target to overcome Taxol-associated chemotherapy resistance in cancer." (PMID 36672454, 2023). "However, the mechanism by which FL118 regulates multiple cancer‐associated proteins (survivin, Mcl‐1, XIAP and cIAP2) is unknown and requires further study." (PMID 35604033, 2022).
cancer (continued). "Moreover, Mcl-1 silencing in Dox-resistant MDA-MB-435 cells overexpressing P-gp, BCRP, Mcl-1, and survivin led to the loss of cell viability, suggesting that targeting Mcl-1 could serve as an alternative treatment for Dox-resistant cancer." (PMID 33919902, 2021). "Due to the neutralization of a broad spectrum of proapoptotic Bcl-2 proteins, Mcl-1 may compensate for the loss of other antiapoptotic Bcl-2 proteins in tumor cells, suggesting it as a potential key regulator of antiapoptotic control in cancer cells." (PMID 34028599, 2021). "The potential function of Mcl-1 in the establishment and maintenance of tumor microenvironment, including tumor-associated immune cells and fibroblasts, for tumor initiation and progression in different cancer types would be an interesting avenue for future research." (PMID 34336857, 2021). "Additionally, MCL1 amplification was associated with cancer recurrence (χ2 test, p = 0.031)." (PMID 32527042, 2020). "Ubiquitin specific peptidase 9x (USP9X), a deubiquitinase belonging to USP family, can stabilize MCL1 through removing the polyubiquitin chains linked by Lys-48 which is the essential sign in proteasomal degradation process, and it is overexpressed in several kinds of cancer cells." (PMID 25685062, 2015). "Further, MCL‐1 regulates long‐chain fatty acid β‐oxidation in cancer cells through its interaction with Acyl‐CoA synthetase long‐chain family member 1 (ACSL1), an enzyme responsible for the conversion of free long‐chain fatty acids into fatty acyl‐CoA esters." (PMID 41420072, 2026). "AZD5991 binds to Mcl‐1 and induces cancer cell apoptosis, which has been applied in hematological malignancies." (PMID 41584728, 2026). "STAT3 activation is achieved by increased phosphorylation at Tyr705, leading to enhanced expression of anti-apoptotic proteins like Bcl-2 and Mcl-1 and increased migratory, invasive, and metastatic potential of cancer cells." (PMID 41596231, 2026). "Caveolin-1 (Cav-1) promotes anoikis resistance in cancer cells by stabilizing anti-apoptotic proteins like Mcl-1 and activating survival pathways such as Src/EGFR/ITGB1, PI3K/Akt, and MEK/ERK, facilitating anchorage-independent growth and metastasis." (PMID 41596231, 2026). "Proteins such as Mcl-1, Cav-1, Bcl-xL, and 14-3-3ζ are suppressors of anoikis, and their up-regulation induces anoikis resistance in cancer cells." (PMID 41596231, 2026). "Inhibition of MCL-1 results in decreased oxidation of long-chain fatty acids (LCFAs) in cancer cells, likely due to the disrupted interaction between MCL-1 and the BH3-like domain of acyl-CoA synthetase long-chain family member 1 (ACSL-1)." (PMID 41427398, 2025). "On the other hand, our results raise a caution for clinical contexts: Mcl-1 is a prominent target in cancer therapy because many tumors rely on Mcl-1 for survival and chemoresistance." (PMID 40951311, 2025). "Recent studies have highlighted the significant role of MCL1 in tumor initiation, cancer cell survival, and resistance to multiple anti-cancer treatments." (PMID 39931465, 2025). "Given Mcl-1’s frequent overexpression and its role in chemoresistance, particularly in cancers reliant on Mcl-1 for survival, inhibitors directly targeting Mcl-1 are actively being developed." (PMID 40841912, 2025). "Taken together, these data highlight that the anti-apoptotic BCL2 proteins BCL2, BCL-XL, and MCL1 are all highly promising therapeutic targets in multiple cancer types." (PMID 40113751, 2025). "Of naturally occurring marinopyrroles and pyrrolomycins, marinopyrrole A was the first to be characterized for cancer cell cytotoxicity, demonstrating preferential toxicity toward cancer cells with elevated Mcl-1 expression compared to healthy cells." (PMID 41149606, 2025).
cancer (continued). "Conversely, anti-apoptotic family members, such as Bcl-2, Bcl-xL, and Mcl-1 (detailed in Section Bcl-2 family proteins in certain cancer types and Anti-apoptotic (pro-survival) Bcl-family proteins in cancer), function as guardians of cell survival." (PMID 40841912, 2025). "Genetic analysis highlights the importance of BCL-XL and MCL1 across different cancer types and the possible utility of BH3-mimetics targeting these proteins." (PMID 40113751, 2025). "A key challenge moving forward is to precisely map the specific E3 ligases and DUBs that are most relevant in different cancer types and to identify strategies to selectively modulate their activity to destabilize Mcl-1." (PMID 40841912, 2025). "The Bcl-2 family’s anti-apoptotic proteins, particularly Mcl-1, offer a viable avenue for cancer treatment since cancer cells can undergo apoptosis when their selective suppression occurs." (PMID 40286038, 2025). "Prior studies have demonstrated that sensitivity of cancer cells to MCL-1 inhibition is inversely related to BCL-XL expression level and the capacity for BCL-XL to neutralize pro-apoptotic BH3 proteins such as BIM60,61." (PMID 40316540, 2025). "The induced apoptosis was evidenced by annexin V binding and an increased expression of the Mcl-1 protein in cancer cells versus normal melanocytes, suggesting that BA is a promising candidate for use as a monotherapy and in combination with radiotherapy." (PMID 40427124, 2025). "Amplification of the MCL-1 gene is one of the most common genetic alterations observed in cancer, and MCL-1 is overexpressed in both hematologic malignancies and solid tumors." (PMID 40204952, 2025). "MCL-1 has significant oncogenic potential and is frequently upregulated in various human cancers, including solid tumors and hematologic malignancies." (PMID 40380182, 2025). "USP9X stabilizes the anti-apoptotic MCL1 protein and promotes myeloma cell survival, and its inhibition is proposed to sensitize cancer cells to chemotherapy." (PMID 39851497, 2025). "Early on, marinopyrrole A was reported as a selective inhibitor of the anti-apoptotic protein Mcl-1, a validated target for cancer treatment and a likely mediator of its cytotoxic activity." (PMID 41149606, 2025). "Marinopyrrole A, a marine-derived natural product, exemplified this potential by inducing proteasomal degradation of Mcl-1, thereby sensitizing resistant cancer cells to Bcl-2 inhibitors and TRAIL-based therapies." (PMID 41149606, 2025). "Cross-coupling of 16 was employed to introduce the 2-fluorofuran fragment into targeted molecules in the development of inhibitors of MCL1 for cancer therapy." (PMID 40509193, 2025). "S63845 is a well-established inhibitor of Mcl-1 that triggers apoptosis in a number of cancer cells." (PMID 39753884, 2025). "In contrast, BH3 profiling directly assesses the functional relevance of MCL1 as a potential therapeutic target in cancer cells." (PMID 39912943, 2025). "Aberrant splicing of Mcl-1 generates the anti-apoptotic Mcl-1L (long) instead of the pro-apoptotic Mcl-1S (short), which inhibits apoptosis and promotes cancer progression." (PMID 40282556, 2025). "Over-expression of oncoproteins Bcl-2 and Mcl-1 led to the evasion of cancer cell apoptosis and promoted cancer cell survival." (PMID 40141366, 2025). "Reducing the high level of MCL1 in tumors has been suggested as a mechanism of action of several anti-cancer agents targeting mTOR signaling." (PMID 41326406, 2025). "Given that changes in cellular redox state affect cancer cell fate, we investigated the crosstalk between intracellular redox milieu and Mcl-1 upregulation in VEN-resistant cells." (PMID 40707672, 2025). "Given Mcl-1’s frequent overexpression and its role in chemoresistance, particularly in cancers reliant on Mcl-1 for survival, selective inhibitors targeting Mcl-1 are actively being developed." (PMID 40841912, 2025).